SNRPGP15 (small nuclear ribonucleoprotein polypeptide G pseudogene 15)
Description:
Associated with snRNP U1, U2, U4/U6 and U5.
Gene: Processed pseudogene on chromosome 19 (14,489,388 to 14,489,609, forward strand). Ensembl gene ENSG00000224543.
Subcellular location: Nucleus